SNORD114-11 (small nucleolar RNA, C/D box 114-11)
Synonyms: 14q(II-11)
Gene: Small nucleolar RNA gene on chromosome 14 (100,968,111 to 100,968,185, forward strand). Ensembl gene ENSG00000200608.
Gene Ontology:
Biological process: RNA processing
Cellular component: nucleolus
Homologues: Orthologues: chimpanzee SNORD114-11 (99% identical), macaque SNORD114-11 (96% identical), mouse Gm23736 (69% identical), rat Snord113l1 (65% identical), mouse Gm22981 (64% identical), rat LOC120093391 (63% identical), mouse AF357341 (57% identical), mouse AF357428 (57% identical), mouse Gm25856 (55% identical). Paralogues in human: SNORD114-13 (83% identical), SNORD114-3 (83% identical), SNORD114-1 (80% identical), SNORD114-16 (79% identical), SNORD114-23 (79% identical), SNORD114-15 (77% identical), SNORD114-17 (77% identical), SNORD114-2 (77% identical), SNORD114-18 (76% identical), SNORD114-20 (76% identical), SNORD114-21 (76% identical), SNORD114-26 (76% identical), and 26 more.